DHFR2 (dihydrofolate reductase 2)
Description:
Key enzyme in folate metabolism. Contributes to the de novo mitochondrial thymidylate biosynthesis pathway. Required to prevent uracil accumulation in mtDNA. Binds its own mRNA and that of DHFR.
Synonyms: DHFRL1; DHFRP4; FLJ16119
Tractability: Small molecule: it belongs to a druggable protein family. PROTAC: ubiquitination databases record sites on it.
Gene: Protein-coding gene on chromosome 3 (94,047,836 to 94,063,389, reverse strand). Ensembl gene ENSG00000178700.
Subcellular location: Mitochondrion; Mitochondrion matrix; Mitochondrion inner membrane
Subcellular location (Human Protein Atlas): Mitochondria
Pathways (Reactome):
Metabolism: Metabolism of folate and pterines
Gene Ontology:
Molecular function: dihydrofolate reductase activity; mRNA binding; protein binding; folate reductase activity; NADP binding
Biological process: tetrahydrofolate metabolic process; thymidine biosynthetic process; dihydrofolate metabolic process; folic acid metabolic process; tetrahydrofolate biosynthetic process; pyrimidine-containing compound biosynthetic process
Cellular component: mitochondrial inner membrane; mitochondrial matrix; mitochondrion; cytosol
Genetic constraint (gnomAD): Loss-of-function variants: 9 observed, 11.88 expected, observed/expected ratio (o/e) 0.76, 90% interval 0.46 to 1.32. The upper end of that interval is the gene's LOEUF score, 1.32, which puts it in group 5 of 6, group 1 being the genes least tolerant of losing a copy. Missense variants: 178 observed, 213.74 expected, observed/expected ratio (o/e) 0.83, 90% interval 0.74 to 0.94. Synonymous variants: 84 observed, 76.11 expected, observed/expected ratio (o/e) 1.1, 90% interval 0.92 to 1.32.
Homologues: Orthologues: chimpanzee DHFR2 (98% identical), dog DHFR (87% identical), mouse Dhfr (87% identical), tropical clawed frog dhfr (59% identical), zebrafish dhfr (59% identical), macaque DHFR2 (53% identical), Drosophila melanogaster Dhfr (44% identical), zebrafish zgc:153031 (39% identical), Caenorhabditis elegans dhfr-1 (35% identical), tropical clawed frog dhfr (33% identical). Paralogues in human: DHFR (92% identical), TYMS (24% identical).
Diseases named in the same sentence as DHFR2 in open-access papers:
DHFR2 is named in the same sentence as 3 diseases in open-access papers, as found by Europe PMC text mining. Sharing a sentence is not in itself a finding about the gene and the disease.
renal carcinoma (1 paper, 2025). A carcinoma arising from the epithelium of the renal parenchyma or the renal pelvis.
DHFR2 also shares sentences with these, for which no sentence is quoted: neural tube defect (1 paper); Stroke (1).